S100A9 (S100 calcium binding protein A9)
Diseases named in the same sentence as S100A9 in open-access papers (continued):
Sharing a sentence is not in itself a finding about the gene and the disease.
atherosclerosis (32 papers, 2006 to 2026). A disease characterized by the build-up of fatty material and calcium deposition in the arterial wall resulting in partial or complete occlusion of the arterial lumen. "S100A9, a candidate for human cardiovascular risk indicators, promotes atherosclerosis in a mouse model." (PMID 36531717, 2022). "The damage-associated molecular pattern molecule CRP and S100A9 are important factors in the inflammatory process of atherosclerosis." (PMID 33167400, 2020). "In addition, increased levels of the serum S100A8 and S100A9 have been reported in diseases such as acute coronary syndrome, coronary artery calcification, cardiovascular intimal hyperplasia, and atherosclerosis, which have a strong association with dyslipidemia." (PMID 40191205, 2025). "Studies have indicated that S100A9, as an inflammatory mediator, is noticeably increased in atherosclerosis and contributes to its development." (PMID 38504474, 2024). "Previous studies have found that S100A8 and S100A9 are related to obesity, insulin resistance, and atherosclerosis." (PMID 34055926, 2021). "There have been several studies on S100A8/S100A9 expression in neutrophils, endothelial cells, smooth muscle cells, and myocardial cells in the initial development of atherosclerosis, but there are few reports on S100A8/S100A9 expression in EAT." (PMID 31534454, 2019). "Increased plasma levels of S100A8 and S100A9 can serve as marks for human cardiovascular disease, and their deletion protects aganist atherosclerosis to some degree." (PMID 26944061, 2016). "Recently, there have been several publications exploring the relationship among obesity, atherosclerosis, and serum levels of S100A9." (PMID 25993652, 2015). "The pattern of cytokine and S100A9/S100A8 up-regulation characterizes atherosclerosis as a proinflammatory disorder." (PMID 19134193, 2009). "Following IL-17Ai intervention, both skin lesions and early atherosclerosis markers significantly improved, accompanied by downregulation of the proinflammatory peripheral blood factor S100A9 and upregulation of anti-inflammatory lipid peroxidation metabolites (e.g., 17(R)-RVD1)." (PMID 42058202, 2026). "Genetic ablation of S100A9 in Apo E-/- mice alleviates the progression of atherosclerosis." (PMID 38164183, 2024). "For instance, some proteins related to atherosclerosis were down-regulated in SF, such as ARG2, CD14, CD44, engulfment, and cell motility protein 1 (ELMO1), neutrophil gelatinase-associated lipocalin (LCN2), MPO, S100A8, or S100A9." (PMID 34572333, 2021). "This suggests that S100A9 may be a critical mediator of microcalcification in atherosclerosis." (PMID 38504474, 2024). "This suggests that S100A9 may be both a biomarker for and regulator of atherosclerosis." (PMID 36531717, 2022). "Thus, blocking heterodimeric S100A8/S100A9 might represent a novel therapeutic modality in treating atherosclerosis." (PMID 16573830, 2006). "Myeloid‐restricted Slc2a1 (GLUT1) deletion or pharmacological S100A8/S100A9 inhibition attenuated TIH‐induced myelopoiesis and atherosclerosis." (PMID 41489606, 2026). "This indicates the activation of the S100A9‐RAGE axis by TIH leading to elevated levels of inflammatory factors, ultimately contributing to atherosclerosis." (PMID 38504474, 2024). "Conversely, studies have revealed that the inhibition of S100A9 holds pivotal therapeutic significance in a plethora of CVD, encompassing atherosclerosis, MI, PAH, PAD, cardiomyopathy, and myocarditis." (PMID 38504474, 2024). "Myeloid‐restricted deletion of Slc2a1 (GLUT1) or pharmacological inhibition of S100A8/S100A9 reduced TIH‐induced myelopoiesis and atherosclerosis." (PMID 37779347, 2023). "The S100 proteins S100A8, S100A9, and S100A12 play a crucial role in inflammation and atherosclerosis, while S100A1 plays a role in post-ischemic angiogenesis." (PMID 35203642, 2022).
atherosclerosis (continued). "Both VCAM-1 and S100A9-targeted TMV nano-system exhibited a distinct tropism to the plaque, indicating the tendency to apply TMV-based VNPs for imaging and the possibility to deliver drugs for the treatment of atherosclerosis." (PMID 34099630, 2021). "A recent review on S100A8 and S100A9 involvement in cardiovascular biology and disease indicate that increased plasma levels of S100A8/A9 predict cardiovascular events in humans, and deletion of these proteins partly protects mice from atherosclerosis." (PMID 23209553, 2012). "Heterodimeric S100A8/S100A9, the form measued in this study, but not the monomeric forms, has been shown to increase detrimental effects caused by advanced end glycation products (AGEs) and may therefore play a role in triggering atherosclerosis in subjects associated with high levels of AGEs." (PMID 19823685, 2009). "Indeed, plasma S100A8/S100A9 correlates with leukocyte counts and coronary artery disease (CAD) in type 1 diabetes (T1D), suggesting that targeting of the S100A8/S100A9‐RAGE axis may reduce atherosclerosis and cardiovascular events in diabetic individuals with adequate glycaemic control." (PMID 41489606, 2026).
Alzheimer disease (30 papers, 2010 to 2025). A progressive, neurodegenerative disease characterized by loss of function and death of nerve cells in several areas of the brain leading to loss of cognitive function such as memory and language. "In this work, we investigate the cross-interaction between the Alzheimer’s disease-related Tau protein and a pro-inflammatory S100A9 protein, which has recently been implicated as a possible modulator of amyloid aggregation." (PMID 41009529, 2025). "The same observation was noted in association with Alzheimer’s disease, where a high concentration of S100A9 resulted in the impaired mobility and proliferation of immune cells, indicating neurotoxicity during acute inflammatory conditions." (PMID 39125762, 2024). "Of note, increased expression of S100B, S100A4, S100A6, S100A8, and S100A9 has also been linked with Alzheimer's disease." (PMID 38737767, 2024). "In cerebrospinal fluid of patients with Alzheimer’s disease, significantly lower levels of S100A9 protein has been observed compared with controls." (PMID 38528588, 2024). "The S100A9 EpiScore is of particular interest as it has been previously identified as a potential biomarker of Alzheimer’s disease." (PMID 38528588, 2024). "A reduction in S100A9 in an Alzheimer’s disease mouse model resulted in less amyloid beta plaques and less cognitive impairment." (PMID 38528588, 2024). "The S100A9 protein is abundant in the brain, and increased levels of S100A9 have been found in the brains of Alzheimer’s Disease (AD) patients, making it a robust biomarker for AD." (PMID 39334857, 2024). "Increasing evidence suggests that the calcium-binding and proinflammatory protein S100A9 is an important player in neuroinflammation-mediated Alzheimer’s disease (AD)." (PMID 38396791, 2024). "The pro-inflammatory mediator and highly amyloidogenic protein S100A9 is involved in the amyloid-neuroinflammatory cascade in Alzheimer’s disease." (PMID 29866153, 2018). "In Alzheimer’s disease, S100A9 was found to be abundant both in neuronal cells and in amyloid plaques, prompting co-aggregation with amyloid-β (Aβ), the major amyloidogenic peptide in Alzheimer’s disease." (PMID 29866153, 2018). "Pro-inflammatory and amyloidogenic S100A9 protein is an important contributor to Alzheimer’s disease (AD) pathology." (PMID 30150640, 2018). "S100A9 was found to be predominantly expressed in neuronal cells, which is similar to the previous observations in the Alzheimer’s disease brain tissues." (PMID 29866153, 2018). "Our previous study presented evidence that the inflammation-related S100A9 gene is significantly upregulated in the brains of Alzheimer's disease (AD) animal models and human AD patients." (PMID 24586443, 2014). "Knockdown of S100A9 expression improves cognition function in Alzheimer's disease model mice (Tg2576) and these animals also exhibit reduced amyloid plaque burden." (PMID 22457725, 2012). "In Alzheimer’s disease, increased levels of S100A9 during inflammation could lead to amyloid formation and deposition." (PMID 39125762, 2024). "YKL-40 effects are further complicated by the YKL-40 inhibition of Receptor for advanced glycation end products (RAGE) activation by S100A9, which may be more relevant in Alzheimer’s disease than ALS." (PMID 36614029, 2022). "Moreover, S100A9 co-aggregates and forms joint complexes with major amyloid polypeptides, such as amyloid β (Aβ) peptide in Alzheimer’s disease and with α-synuclein in Parkinson’s." (PMID 34445262, 2021). "Importantly, the immune-response genes of Lcn2, S100a8, and S100a9 have been found that markedly increased in the patients’ hippocampus with Alzheimer's disease." (PMID 34565419, 2021). "This hypothesis is in line with earlier findings in patients with Alzheimer’s disease documenting the increased level of fecal calprotectin and S100A9 level in cerebrospinal fluid." (PMID 31611762, 2019).
Alzheimer disease (continued). "It has therefore been suggested that pro-inflammatory S100A9, which possesses intrinsic amyloidogenic properties as well as the ability to modulate Aβ aggregation, can serve as a link between the Alzheimer’s disease amyloid and neuroinflammatory cascades and as a prospective therapeutic target." (PMID 29866153, 2018). "At the same time, it is also observed a striking decrease in the expression of S100A8 and S100A9 in CD11c+ cells which surround the amyloid plaques and might play a beneficial immune-modulatory role in Alzheimer’s disease (AD)." (PMID 29942307, 2018). "This indicates that the pathogenic conditions associated with oxidative stress and amyloid self-assembly in amyloid diseases such as PD and Alzheimer’s disease may induce expression of S100A9 in neurons." (PMID 29866153, 2018). "We suggest here that sustained neuroinflammation promoting the spread of amyloidogenic S100A9 in the brain tissues can be a trigger of the amyloid cascade involving α-syn and leading to PD development, similar to the effect of S100A9 on Aβ aggregation in the Alzheimer’s disease." (PMID 29866153, 2018). "Here, we provide insights into S100A9 specific mechanisms of action in Alzheimer’s disease (AD)." (PMID 24240735, 2014). "Among them S100B, S100A6, S100A9 and S100A12 have been linked to Alzheimer's Disease." (PMID 20672051, 2010). "Also, S100A9 carries amyloidogenic properties and, hence, could contribute to Alzheimer’s Disease pathology." (PMID 40320180, 2025). "Consequently, focusing on S100A9 during the prolonged inflammatory phase of Alzheimer’s disease could offer a potentially effective therapeutic strategy." (PMID 39796257, 2025). "S100A9 levels have been found to increase in the serum of patients with MS and the protein may also be involved in the pathology of other CNS diseases, such as Alzheimer’s disease and stroke." (PMID 36430692, 2022). "In this study, we have focused on the involvement in PD pathology of the specific pro-inflammatory mediator S100A9, which we have found to play a critical role in connecting neuroinflammatory and amyloid pathologies into the integrated amyloid-neuroinflammatory cascade in Alzheimer’s disease." (PMID 29866153, 2018). "We suggest that sustained neuroinflammation promoting the spread of amyloidogenic S100A9 in the brain tissues may trigger the amyloid cascade involving α-syn and S100A9 and leading to PD, similar to the effect of S100A9 and Aβ co-aggregation in Alzheimer’s disease." (PMID 29866153, 2018). "Our results highlight a shared neuroinflammatory signature across Alzheimer’s disease (AD), Parkinson’s disease (PD), and Huntington’s disease (HD), characterized by the dysregulation of hub genes such as MMP9, S100A8, S100A9, CCL2, and LCN2." (PMID 41614741, 2025). "Analysis of previously published GE data in Late Onset Alzheimer’s Disease (LOAD) (NCBI GEO: GSE44770,), show that S100A8 and S100A9 are among the highest up-regulated genes in LOAD." (PMID 32469975, 2020). "While the topic of inflammation in neurodegeneration is well discussed, here we present specific culprit – S100A9, and specific mechanism – S100A9 amyloid formation, which can drive TBI-induced inflammation to the amyloid cascade in Alzheimer’s disease." (PMID 30150640, 2018). "Due to its inherent amyloidogenicity, S100A9 may play a more important role in PD pathology than merely being one of the disease-related pro-inflammatory mediators: it may contribute to the development of the PD amyloid-neuroinflammatory cascade in a similar way in Alzheimer’s disease." (PMID 29866153, 2018). "Both proteins are known to be expressed in neuronal cells, and the elevated levels of S100A9 have been reported in Alzheimer’s disease and aging; however, no information is available for PD-affected brain tissues." (PMID 29866153, 2018). "Evidence indicates that S100A9 contributes to Alzheimer’s disease (AD) pathology, although the precise mechanisms are not clear." (PMID 23721320, 2013).
Alzheimer disease (continued). "Moreover, in mice models of Alzheimer’s disease and traumatic brain injury, we also detected depositions of S100A9, but not S100A8." (PMID 34445262, 2021). "These S100 family members, namely S100A1, S100A6, S100A7, S100A8, S100A9, S100A12, and S100B, seem to be involved in the progression of Alzheimer’s disease (AD), including the formation of amyloid aggregates, and could thereby be promising regarding new therapeutic approaches." (PMID 32722137, 2020). "However, a mechanistic link between S100A9 and Alzheimers disease pathology has not been shown." (PMID 22457725, 2012). "Furthermore, S100A9 forms amyloid complexes with Aβ, by templating on the Aβ fibrillar surface, which may also contribute to the development of joint amyloid deposits in Alzheimer’s disease, though these polypeptides do not form a mixed cross-β-sheet." (PMID 34445262, 2021).
autoimmune disease (30 papers, 2010 to 2025). A disorder resulting from loss of function or tissue destruction of an organ or multiple organs, arising from humoral or cellular immune responses of the individual to their own tissue constituents. "Dysregulated S100A8/S100A9 expression has been linked to various inflammatory and autoimmune diseases." (PMID 41476978, 2025). "Abnormal expression and aberrant function of S100A8/S100A9 are closely associated with the onset and progression of a wide range of diseases, including inflammatory diseases, tumors, and autoimmune diseases." (PMID 41476978, 2025). "Expressed strongly by myeloid cells, damage-associated molecular pattern (DAMP) proteins S100A8 and S100A9 are found in the serum of patients with infectious and autoimmune diseases." (PMID 31437241, 2019). "S100a8 and s100a9 are in the focus of rigorous research due to their association with numerous diseases, including acute and chronic inflammatory diseases, autoimmune diseases, cancer, and neurodegenerative diseases." (PMID 28769105, 2017). "S100A8 and S100A9 expression levels increased in many types of cancer, neurodegenerative disorders, inflammatory and autoimmune diseases and they are implicated in the numerous disease pathologies." (PMID 22489132, 2012). "Additionally, multiple studies have reported that the S100A9 gene is associated with inflammatory diseases, autoimmune disease and infections." (PMID 36718447, 2023). "This suggests a strong association between the presence of autoimmune disease markers S100A8 and S100A9 and the development of spontaneous ankylosing spondylitis in crab-eating monkeys." (PMID 39877611, 2025). "Several previous studies performed that S100A8/S100A9 can show a pro-inflammatory activity in some autoimmune diseases and these genes were reportedly upregulated in inflammatory states." (PMID 40540498, 2025). "al, on a group of quinoline-3-carboxamide drugs, known for reducing inflammation and symptoms of autoimmune disease, led to the discovery of binding by S100A9 to TLR4 as a main target of these drugs." (PMID 39497822, 2024). "S100A8 and S100A9 have been shown to mediate both beneficial defense against pathogens and pathological inflammation in autoimmune diseases, demonstrating their proinflammatory potential." (PMID 39497822, 2024). "The upregulation of S100-A9 occurs in multiple immune system dysfunction diseases that result in excessive immune responses leading to autoimmune diseases and hypersensitivity reactions." (PMID 35565595, 2022). "S100A8 and S100A9, both secreted factors associated with the ECM, have been associated with acute and chronic inflammatory conditions and autoimmune diseases." (PMID 36672527, 2022). "S100A8 and S100A9 which are mainly expressed in myeloid cells naturally form a stable heterodimer and involve in inflammatory processes that lead to autoimmune diseases and many human cancers." (PMID 33294444, 2020). "Paquinimod may have potential therapeutic applications as an S100A8/S100A9 inhibitor, as excessive release of S100A8/S100A9 is associated with the occurrence and development of various inflammatory and autoimmune disorders." (PMID 41476978, 2025). "S100A8 and S100A9 levels are markedly increased in a wide range of inflammatory conditions, including autoimmune diseases, cancers, and neurodegenerative disorders, and they may serve as effective biomarkers for disease detection and prognosis." (PMID 40948742, 2025). "Human clinical studies have already established a link between S100A8 and S100A9 and autoimmune-related arthritic diseases, suggesting that the spontaneous spondyloarthritis observed in crab-eating macaques may be related to autoimmune diseases." (PMID 39877611, 2025). "Increasing evidence indicates that the S100A9 protein could be a new biomarker for inflammation and autoimmune diseases." (PMID 39596686, 2024).
autoimmune disease (continued). "S100A9 is a calcium-binding protein highly expressed in the cytosol of neutrophils and monocytes, and participates in multiple inflammatory processes including bacterial infections, autoimmune diseases, complement activation and even aging processes." (PMID 33057112, 2020). "The S100A8/S100A9 complex is the most abundant DAMP in many autoimmune diseases." (PMID 32075957, 2020). "Moreover, S100A8 and S100A9 serve as inflammatory biomarkers in several autoimmune disorders, such as systemic lupus erythematosus and inflammatory bowel disease." (PMID 31023360, 2019). "Neutralizing the activity of these molecules might be helpful in the treatment of inflammation associated with RA, as well as with other chronic inflammatory and autoimmune diseases where S100A9 and calprotectin are oversecreted." (PMID 23029038, 2012). "The CD52+ Mo-Mp subtype expressed CD52, S100A9 and S100A8, which has been reported as a bi-directional regulator in inflammation of autoimmune diseases via T cell activation and Treg induction." (PMID 38601143, 2024). "Recently, several reports have provided evidence that S100A9 can exert anti-inflammatory effects by inducing the migration of MDSC in tumor-bearing individuals and autoimmune diseases." (PMID 31417498, 2019). "Although this post-translational form of S100A9 could be a determinant player for the development of chronic and autoimmune diseases, the presence of S100A8/A9-P in clinical samples has not yet been investigated to support this assumption." (PMID 31739406, 2019).